PRKCI (protein kinase C iota)
Diseases named in the same sentence as PRKCI in open-access papers (continued):
Sharing a sentence is not in itself a finding about the gene and the disease.
osteosarcoma (4 papers, 2024 to 2025). A usually aggressive malignant bone-forming mesenchymal neoplasm, predominantly affecting adolescents and young adults. "This study aimed to explore the biological function of PRKCI in osteosarcoma and its potential molecular mechanism." (PMID 39015499, 2024). "This suggested that the knockdown of PRKCI inhibited the proliferation of osteosarcoma cells by arresting the cell cycle at the G2/M phase in SW1353 cells, with barely a difference in U2OS cells." (PMID 39015499, 2024). "PRKCI expression was evaluated in osteosarcoma cell lines using Western blot analysis and reverse transcription PCR." (PMID 39015499, 2024). "Taken together, these results indicated that PRKCI played an important role in osteosarcoma and was related to the malignancy of osteosarcoma." (PMID 39015499, 2024). "In this study, we detected the expression of PRKCI in osteosarcoma cell lines and observed its effects on osteosarcoma cell proliferation, cell cycle, migration, and invasion by upregulating or silencing the expression of PRKCI." (PMID 39015499, 2024). "Subsequently, the CCK-8 assay showed that knockdown of PRKCI significantly inhibited the growth of osteosarcoma cells with time dependence." (PMID 39015499, 2024). "In order to further clarify the effect of PRKCI on the biological characteristics of osteosarcoma cells, the changes in SW1353 and U2OS cell proliferation after silencing PRKCI were investigated." (PMID 39015499, 2024). "In this study, we explored the tumorigenic effect of PRKCI in osteosarcoma by cell experiment and histological analysis." (PMID 39015499, 2024). "It suggested that PRKCI was closely related to the tumorigenicity of osteosarcoma, and the Akt/mTOR signaling pathway was involved in this process." (PMID 39015499, 2024). "In order to explore the role of PRKCI in osteosarcoma cells, the effect of PRKCI-overexpression on the proliferation of osteosarcoma cells (SW1353 and U2OS) was studied by the CCK-8 assay and colony-forming assay." (PMID 39015499, 2024). "Overall, these results suggest that PRKCI depletion inhibits osteosarcoma cell growth via inactivation of the Akt-mTOR pathway." (PMID 39015499, 2024). "This laid the foundation for exploring innovative therapeutic strategies targeting PRKCI for the treatment of osteosarcoma." (PMID 39015499, 2024). "The migration and invasion of osteosarcoma cells were first detected by the Transwell system in the presence of PRKCI-overexpression and PRKCI-silencing." (PMID 39015499, 2024). "The mRNA and protein expression levels of PRKCI in one osteosarcoma cell line (U2OS), one human osteoblast cell line (Saos2), and one human chondrosarcoma cell line (SW1353) were detected by RT-PCR and Western blot analyses." (PMID 39015499, 2024). "Knockdown of PRKCI inhibited the proliferation of osteosarcoma cells by inactivating the Akt/mTOR signaling pathway, suggesting that PRKCI was a potential target for osteosarcoma therapy." (PMID 39015499, 2024). "Here, we have found that the Akt-mTOR signaling pathway was involved in the inhibitory effect of PRKCI on osteosarcoma in vitro." (PMID 39015499, 2024). "At the same time, the expression of PRKCI in tumor tissue was only related to histological type, indicating that PRKCI was related to the tumorigenicity of osteosarcoma." (PMID 39015499, 2024). "Based on the biological role of PRKCI in osteosarcoma cell lines, the expression of PRKCI in osteosarcoma tissues and adjacent tissues of 42 patients was detected by the IHC to further explore its role in human osteosarcoma." (PMID 39015499, 2024). "Flow cytometry was used to determine the changes in the cell cycle in osteosarcoma cells after the knockdown of PRKCI." (PMID 39015499, 2024). "In conclusion, our study found that PRKCI was overexpressed in osteosarcoma cell lines and tissues and promoted the proliferation and migration of cancer cells." (PMID 39015499, 2024).
osteosarcoma (continued). "Simultaneously, the expression of SQSTM1 in tumor tissues was not related to clinical characteristics, and SQSTM1 interacted with PRKCI in U2OS cells, suggesting that SQSTM1 and PRKCI played a crucial role in osteosarcoma." (PMID 39015499, 2024). "Our study found that PRKCI was overexpressed in osteosarcoma cell lines." (PMID 39015499, 2024). "Comparison of PRKCI protein expression in osteosarcoma and cancer-adjacent tissues." (PMID 39015499, 2024). "The CCK-8 assay, colony formation assay, flow cytometry, Transwell assay, and wound-healing assay were used to detect the proliferation, colony-forming capacity, cell cycle, migration, and invasion of osteosarcoma cells when PRKCI was overexpressed or knocked down." (PMID 39015499, 2024). "SQSTM1, which interacted with PRKCI, was also overexpressed in osteosarcoma." (PMID 39015499, 2024). "The correlation between PRKCI expression and clinical characteristics of osteosarcoma patients." (PMID 39015499, 2024). "Finally, the protein molecule expression of the Akt/mTOR signaling pathway in osteosarcoma was detected when PRKCI was knocked down." (PMID 39015499, 2024). "Finally, we explored the relationship between PRKCI and the Akt/mTOR signaling pathway in osteosarcoma cell lines." (PMID 39015499, 2024). "Furthermore, overexpression of PRKCI promoted the proliferation and colony-forming capacity of osteosarcoma cells while silencing PRKCI inhibited the proliferation, colony-forming capacity, migration, and invasion of osteosarcoma cells." (PMID 39015499, 2024). "Results showed that PRKCI was overexpressed obviously in osteosarcoma and chondrosarcoma cell lines compared with osteoblast lines, which indicated that PRKCI might play an important role in osteosarcoma tumorigenesis." (PMID 39015499, 2024). "Furthermore, the correlation between PRKCI expression and the clinical characteristics of osteosarcoma patients was explored." (PMID 39015499, 2024). "The overexpression of PRKCI promoted the proliferation and colony-forming capacity of osteosarcoma cells, while silencing PRKCI inhibited the proliferation, colony-forming capacity, migration, and invasion of osteosarcoma cells and arrested the cell cycle at the G2/M phase." (PMID 39015499, 2024). "However, the role of PRKCI in osteosarcoma cells remains to be determined." (PMID 39015499, 2024). "PRKCI is abnormally expressed in various cancers, but its role in osteosarcoma is unknown." (PMID 39015499, 2024). "Then, we detected the expression of PRKCI and SQSTM1 in human osteosarcoma tissues and analyzed their correlation with the clinical characteristics of osteosarcoma, respectively." (PMID 39015499, 2024). "Here, to determine whether they are pathway molecules for PRKCI to inhibit the proliferation of osteosarcoma cells, we detected the molecule expression of Akt-mTOR in SW1353 and U2OS cells when PRKCI was knocked down." (PMID 39015499, 2024). "Our current research elucidated the interaction between PRKCI and SQSTM1, demonstrating that PRKCI upregulated SQSTM1 and mediated critical functions in the proliferation and progression of osteosarcoma cells through the activation of the Akt/mTOR signaling pathway." (PMID 39015499, 2024). "In our study, we found that PRKCI was overexpressed in osteosarcoma cell lines and verified the abnormal expression of PRKCI in osteosarcoma tissues compared with nontumor tissues." (PMID 39015499, 2024). "By comparison, we found that the expression of PRKCI in osteosarcoma was much higher than that in corresponding nontumor tissues (p < 0.0001)." (PMID 39015499, 2024). "The expression of PRKCI and SQSTM1 in osteosarcoma was higher than that in chondrosarcoma." (PMID 39015499, 2024). "In short, the effect of PRKCI on the tumorigenicity of osteosarcoma has not been studied." (PMID 39015499, 2024).
osteosarcoma (continued). "Overexpression of PRKCI enhanced the level of SQSTM1, p-mTOR, and p-AKT and inhibited the level of LC3B-II, indicating that overexpression of PRKCI could enhance the level of SQSTM1 and inhibit the level of autophagy through the Akt-mTOR pathway in osteosarcoma cells." (PMID 39015499, 2024). "Several studies have found abnormal expression of the Akt/mTOR signaling pathway in osteosarcoma, but it is not known whether it is involved in the effect of PRKCI on osteosarcoma." (PMID 39015499, 2024). "According to previous reports, PRKCI is abnormally expressed in cancers of various organs and tissues, including the lung, stomach, colon, breast, bile duct, and prostate, but there are no data on osteosarcoma." (PMID 39015499, 2024). "Furthermore, we identified the interaction between PRKCI and SQSTM1 in osteosarcoma cell lines." (PMID 39015499, 2024). "However, the role of PRKCI in osteosarcoma has not been reported." (PMID 39015499, 2024). "However, the interaction between PRKCI and SQSTM1 in osteosarcoma remains unclear." (PMID 39015499, 2024).
Sepsis (4 papers, 2021 to 2025). Sepsis is defined as life-threatening organ dysfunction caused by a dysregulated host response to infection. "More recently, Wei and colleagues extended these observations by implicating miR-545 and its regulatory axis with circ-PRKCI, linking expression profiles not only to the risk of sepsis but also to severity indices and 28-day mortality." (PMID 41149908, 2025). "A clinical study demonstrated that circ-PRKCI was an independent factor to predict the mortality risk of sepsis patients." (PMID 36425075, 2022). "Decreased circ-PRKCI and increased miR-545 expressions were associated to 28-day mortality risk in sepsis patients, which were slightly lower than the predictive values of APACHE II score and SOFA score for predicting 28-day mortality risk." (PMID 35741168, 2022). "Low levels of circ-PRKCI were correlated with sepsis risk, clinical disease severity and 28-day mortality risk." (PMID 34956235, 2021). "Decreased circ-PRKCI expression and increased miR-545 expression were observed in sepsis patients compared to healthy controls, both of which had close correlations with sepsis risk." (PMID 35741168, 2022). "Finally, tens of circRNAs such as circC3P1, hsa_circRNA_104484, hsa_circRNA_104670 and circVMA21 and circ-PRKCI have been found to affect pathogenesis of sepsis." (PMID 34956235, 2021).
cervical squamous cell carcinoma (3 papers, 2017 to 2024). A squamous cell carcinoma arising from the cervical epithelium. "In TCGA data, genetic changes in PRKCI (gene of PKCiota), including amplification and mutation, occurred in more than 15% of patients with ESCC, ovarian epithelial tumors (OV), non-small cell lung cancer (NSCLC), and cervical squamous cell carcinoma (CSCC)." (PMID 38247539, 2024). "PRKCI overexpression was frequently observed in cervical squamous cell carcinoma." (PMID 29312619, 2017). "SOX2 and PRKCI display lower levels of mRNA over-expression in 3q26-amplified squamous cervical cancers, while MECOM and TERC show no over-expression." (PMID 34436017, 2021).
ovarian serous adenocarcinoma (3 papers, 2009 to 2025). An adenocarcinoma that arises from the ovary and is characterized by the presence of malignant epithelial cells that, in well differentiated tumors, resemble the epithelium of the fallopian tube or, in poorly differentiated tumors, show anaplastic features and marked nuclear atypia. "Bioinformatics analysis showed that ECT2, as a part of the 3q26 amplicon, co-amplified and overexpressed with (protein kinase C iota) PRKCI, and other molecules in ovarian serous cancer." (PMID 40655948, 2025). "The LCM data set shows over-expression of CLDN11, MYNN, PRKCI, and SKIL in ovarian serous adenocarcinoma." (PMID 19419571, 2009). "However, subsequent functional analyses by ectopic overexpression of PRKCI in serous ovarian cancer cell lines failed to alter the proliferation, colony formation or chemoresistance." (PMID 29228547, 2017).
pancreatic cancer (3 papers, 2023 to 2026). "In the prognostic risk model of this study, ZMAT1 is a low-risk gene for pancreatic cancer, while PRKCI and ZNF185 are high-risk genes for pancreatic cancer." (PMID 37396042, 2023). "The paired protein kinases PRKCI and RIPK2 promote pancreatic cancer growth and metastasis through activation of the JNK/ERK pathway via NF-κB phosphorylation." (PMID 41563982, 2026).
squamous cell carcinoma (3 papers, 2019 to 2022). A carcinoma arising from squamous epithelial cells. "Recent study provided evidence that PRKCI mRNA is highly expressed in human squamous cell carcinomas of lung." (PMID 31374089, 2019).
colorectal cancer (2 papers, 2022). A primary or metastatic malignant neoplasm that affects the colon or rectum. "MiR-217-5p could induce apoptosis in colorectal cancer cells by regulating multiple target genes, including PRKCI, BAG3, ITGAV, and MAPK1 in the ERK-MAPK signaling pathway." (PMID 35737029, 2022). "For example, it was uncovered that the apoptosis-inducing potential of miR-217-5p can induced apoptosis via blocking multiple target genes PRKCI, BAG3, ITGAV and MAPK1 in colorectal cancer cells." (PMID 36352482, 2022).
esophageal cancer (2 papers, 2017 to 2021). A primary or metastatic malignant neoplasm involving the esophagus. "Circular RNA PRKCI knockdown inhibits esophageal cancer progression and elevates cell radiosensitivity through regulating the miR-186-5p/PARP9 axis." (PMID 34853591, 2021).
hepatic neoplasm (2 papers, 2017 to 2024). "The interaction among PRKCI and SQSTM1 coordinates the oxidative metabolic reaction in hepatic neoplasm." (PMID 39015499, 2024). "The interaction between PRKCI and SQSTM1 regulates autophagy, thus playing a role in liver cancer development." (PMID 39015499, 2024).
hepatocellular carcinoma (2 papers, 2019 to 2023). A malignant tumor that arises from hepatocytes. "In hepatocellular carcinoma (HCC), miR-186-5p interacted with long non-coding RNA 665 (LINC00665) and circular RNA protein kinase C iota (circ-PRKCI) to inhibit cellular viability and tumor progression by regulating Forkhead Box K1 (FOXK1) expression." (PMID 37841425, 2023).
leukemia (2 papers, 2020 to 2022). A malignant (clonal) hematologic disorder, involving hematopoietic stem cells and characterized by the presence of primitive or atypical myeloid or lymphoid cells in the bone marrow and the blood. "PRKCI is essential for BCR-ABL oncogene-mediated chemoresistance in leukemia cells and prevents drug-induced apoptosis." (PMID 33488754, 2020). "Our study suggests that tamoxifen targets PRKCI that encodes a member of the protein kinase C (PKC) family of serine/threonine protein kinases and is found to be necessary for BCR-ABL-mediated resistance to drug-induced apoptosis and therefore protects leukemia cells against drug-induced apoptosis." (PMID 36559013, 2022).
lung adenocarcinoma (2 papers, 2020 to 2022). A carcinoma that arises from the lung and is characterized by the presence of malignant glandular epithelial cells. "have shown that circ PRKCI was overexpressed in lung adenocarcinoma tissues and promoted the proliferation and tumorigenesis of lung adenocarcinoma." (PMID 36338714, 2022).
oesophagal cancer (2 papers, 2020 to 2022). "BIRC5 knockdown decreased cell proliferation and induced apoptosis in oesophageal cancer cells, whereas PRKCI silencing decreased proliferation, migration, invasion and growth of anchorage-independent colonies of oesophageal cancer cells and induced apoptosis." (PMID 32429269, 2020).
pancreatic adenocarcinoma (2 papers, 2018 to 2022). "Primary PDAC tumors within the TCGA pancreatic adenocarcinoma dataset were segregated by PRKCI mRNA expression level into two groups optimized for survival outcomes." (PMID 35159064, 2022).
autism (1 paper, 2024). Persistent deficits in social interaction and communication and interaction as well as a markedly restricted repertoire of activity and interest as well as repetitive patterns of behavior. "The Protein Kinase C Iota has been implied in immunosuppression, and genetic variation in the PRKCI gene has been found to be associated with bipolar disorder and autism." (PMID 39367879, 2024).
breast tumors (1 paper, 2025). "In contrast, about one-third of breast tumors show CP gene amplification, including SCRIB (14.7%), LLGL2 (7%), PRKCI (protein kinase C, iota) (5%), PARD6B (partitioning defective 6 homolog beta) (4.9%), DLG1 (3.92%), and DLG2 (discs large homolog 2) (3.92%)." (PMID 40057606, 2025).
clear cell ovarian carcinoma (1 paper, 2017). "The results indicated the potential use of ATM in the treatment of PRKCI overexpressed clear cell ovarian cancer." (PMID 29228547, 2017). "This study is the first report of an integrated genomic analysis of CCOC through which we have identified for the first time PRKCI as a potential target gene in human clear cell ovarian cancer." (PMID 29228547, 2017). "Until recently, the biological significance of PRKCI in clear cell ovarian carcinoma remains largely unknown." (PMID 29228547, 2017).
endometrial cancer (1 paper, 2021). Primary or metastatic malignant neoplasm involving the endometrium (mucous membrane that lines the endometrial cavity). "Five most significant genes were selected, including L1CAM (L1 cell adhesion molecule), PRKCI, ESR1, CDKN2A and VIM, to construct a prognostic model for endometrial cancer." (PMID 34659539, 2021). "In this study, L1CAM, PRKCI and CDKN2A were the most relevant genes affecting survival in endometrial cancer, with high amounts reflecting poor prognosis." (PMID 34659539, 2021).
glioblastoma (1 paper, 2017). The most malignant astrocytic tumor (WHO grade IV). "It was found that Protein Kinase C Iota (PKCi) was highly expressed in glioblastoma patient-derived CSCs, and silencing PKCi resulted in apoptosis and reduction of proliferation of the glioblastoma CSCs in vitro and tumor growth in vivo in a xenograft mouse model." (PMID 28356914, 2017).
head and neck cancer (1 paper, 2014). A primary or metastatic malignant neoplasm affecting the head and neck. "A significant number of genes were amplified in greater than 30 percent of cancer patients, including DCUN1D1 (43% of lung squamous cancers), FADD and PPFIA1 (∼30% of head and neck cancers), and PRKCI (36% of lung squamous cancers)." (PMID 24874471, 2014).
Hyperglycemia (1 paper, 2019). An increased concentration of glucose in the blood. "Therefore, miR-29c is a negative regulator of axonal growth of DRG neurons by targeting PRKCI under hyperglycemia, confirming the involvement of miRNAs in the molecular mechanisms underlying hyperglycemia-induced axonal damage." (PMID 31540445, 2019).
melanoma (1 paper, 2023). A malignant, usually aggressive tumor composed of atypical, neoplastic melanocytes. "Furthermore, vimentin expression is correlated with the upregulation of N-cadherin, and it has been recently found that in melanoma, protein kinase C-iota (PKC-ι) activates vimentin while inducing EMT." (PMID 37511550, 2023).
ovarian endometriosis (1 paper, 2017). A non-neoplastic disorder characterized by the growth of endometrial tissue in the ovaries. "When compared to our CCOC data (since both datasets were based on the same array platform Affymetrix Human Genome U133 Plus 2.0), PRKCI was found significantly overexpressed in CCOC compared to ovarian endometriosis (3.82-fold, p = 0.0021)." (PMID 29228547, 2017). "In a recently published study interrogating 10 human ovarian endometriosis versus normal uterine endometrium, significant upregulation was observed for PRKCI in ovarian endometriosis (1.81-fold, p = 0.0001)." (PMID 29228547, 2017).
ovarian neoplasm (1 paper, 2021). A benign, borderline, or malignant neoplasm involving the ovary. "In addition, PRKCI upregulation is an early and common event in ovarian neoplasms and promotes an immune-suppressive tumor microenvironment in tumor progression." (PMID 34659539, 2021).